IL7 (interleukin 7)
Diseases named in the same sentence as IL7 in open-access papers (continued):
Sharing a sentence is not in itself a finding about the gene and the disease.
melanoma (continued). "We confirmed the melanoma-specific reactivity of TIL1383I TCR-modified T cells generated following IL-7 culture using both in vitro and in vivo systems." (PMID 34172810, 2021). "IL7-Fc significantly enhanced the efficacy of ACT using pmel-1 CD8+ T cells in our experimental B16-F10 melanoma model." (PMID 34440787, 2021). "Other researchers have also utilized the NDV to express interleukine-7 (IL-7) and interleukine-15 (IL-15) in their studies where the recombinant NDV strain LX/IL7/IL15 showed antitumor activity against murine melanoma cells." (PMID 33354412, 2020). "Four molecules were found to be very good classifiers of the control vs. melanoma samples, namely, IL-1Ra, IL-7, MIP-1a, and MIP-1b, with AUC values of 0.88, 0.86, 0.93, and 0.87, respectively." (PMID 33302400, 2020). "Accordingly, the antitumor activity of IL-7 has been shown in vitro and in vivo in animal models of prostate cancer, melanoma, and some neurological and blood cancers." (PMID 31185636, 2019). "These IL-7/15/21 expanded lymphocytes are capable of inducing regression of metastatic B16 melanoma, even at low doses of cells." (PMID 25903148, 2015). "Here, we report the results of a clinical phase I trial using for the first time autologous, interleukin 7 gene-modified tumour cells for vaccination of ten patients with disseminated malignant melanoma." (PMID 9667667, 1998). "The activity of IL-7-induced LAK cells against two allogeneic melanoma cell lines was 32.7% (+/- 17.9) against SK-Mel-37 and 38.1% (+/- 12.5) against SK-Mel-23 at an effector-to-target (E/T) ratio of 20:1." (PMID 8018541, 1994). "In two patients, IL-7-induced LAK-cell activity against autologous melanoma cells exceeded even that of IL-2 significantly (67% vs 35% and 95% vs 82%)." (PMID 8018541, 1994). "Peripheral blood lymphocytes (PBLs) from 14 patients with stage III melanoma were isolated and incubated in the presence of 1,000 U ml-1 IL-7 and 100 U ml-1 IL-2 for comparison." (PMID 8018541, 1994). "Subsequent replication in a cohort of patients with melanoma supported these findings, suggesting that increased IL-7 expression in B-cells might be the principal mechanism involved." (PMID 40642097, 2025). "This suggests that IL-7 may contribute to melanoma development and could serve as a valuable marker for tumor progression and patient prognosis." (PMID 40636453, 2025). "IL-7 has also shown potential efficacy in the treatment of melanoma." (PMID 38675377, 2024). "Recombinant IL-7-Fc (Chimerigen) has also been used in adoptive cell therapy against melanoma." (PMID 36142322, 2022). "The mechanisms underlying CD8+ T cell responses to IL-7 in melanoma remain not completely elucidated." (PMID 35850640, 2022). "Given that rs16906115 is associated with baseline pre-treatment differences in patient B cell IL7 expression and B cell maturation, we sought to explore whether this SNP had a relationship with the natural history of melanoma." (PMID 36526722, 2022). "We previously showed reduced IL-7 level in melanoma patients." (PMID 35850640, 2022). "In a lymphocytic mouse melanoma model, IL-7-Fc therapy increased inhibition of tumor growth." (PMID 36142322, 2022). "Importantly, CD8+ T cell-induced cytotoxicity or IFN-γ production in response to IL-7 stimulation was still lower in peripheral blood and tumor tissue of melanoma patients." (PMID 35850640, 2022). "In contrast, in an immunocompetent murine melanoma model, IL7-Fc dampened the anti-tumor immunity." (PMID 34440787, 2021). "Furthermore, we demonstrated melanoma-reactivity of TIL1383I TCR-modified cells generated following IL-7 culture using in vitro assays and a superior response in an in vivo melanoma model." (PMID 34172810, 2021). "In addition, we found a superior anti-melanoma response when mice were treated with TIL1383I TCR-modified T cells generated following IL-7 culture compared to mice treated with activated cells." (PMID 34172810, 2021).
melanoma (continued). "Interestingly to notice, the expression of IL-1Ra and IL-7 (known anti-inflammatory cytokines) is significantly reduced in the melanoma samples, while expression of MIP-1a and MIP-1b (known inflammatory chemokines) is significantly increased." (PMID 33302400, 2020). "In this study, we in vitro generated IL-2 and IL-7 effectors derived from congenic mice and assessed vulnerability of IL-2 and IL-7 effectors to Treg cells in vitro, and then in vivo in a mouse model of subcutaneous tumor, B16 melanoma that provides an in vivo Treg-cell-enriched environment." (PMID 28496990, 2017). "Indeed, the blocking of IL‐7R, in a mice model of melanoma, suppressed tumor growth by modifying immune infiltrate suggesting that IL‐7/IL‐7R axis could be an interesting target for therapy." (PMID 36054746, 2022). "Thus, we chose 10 ng/ml of recombinant IL-7 for CD8+ T cells stimulation in melanoma patients." (PMID 35850640, 2022). "A proportion of mice receiving melanoma vaccine co-expressing IL-21 and IL-7 developed vitiligo over time, which possibly suggested that breaking of topical peripheral tolerance to self-antigens, in this case melanocyte-associated antigens, could be achieved using this new vaccine formulation." (PMID 27571893, 2016). "IL-7-targeted therapies have made breakthroughs in several cancer types, including non-small cell lung cancer (NSCLC), lymphoma, colorectal cancer, and melanoma." (PMID 38675377, 2024). "During combination therapy, IL-7–CBD played a key role in the development of immunological memory and prevented B16F10 melanoma regrowth upon rechallenge." (PMID 38019919, 2023). "IL-7 can also induce the production of IL-1α, IL-1β, and TNF-α by monocytes and can also help to inhibit melanoma growth." (PMID 38001643, 2023). "Systemic treatment with IL-7–CBD and CBD–IL-12 significantly improved the survival of poorly immunogenic B16F10 melanoma–bearing mice when compared to either agent in monotherapy." (PMID 38019919, 2023). "Recombinant human IL-7 has been reported to increase CD4+ and CD8+ T cells in the periphery of cancer patients, while the expression of IL-12 in melanoma patients also increases the infiltration of CD8+ cytotoxic T cells into tumors." (PMID 37835433, 2023). "Taken together, the current data indicated that IL-7 promoted CD127 expression and the cytotoxic potential of CD8+ T cell in melanoma patients." (PMID 35850640, 2022). "Consistent with the previous finding in viral infection and cancers, we found that IL-7 promoted peripheral and tissue-infiltrating CD8+ T cell activity in melanoma patients." (PMID 35850640, 2022). "The present study demonstrates, for the first time, that the IL-1Ra, IL-7, MIP-1a, and MIP-1b gene signature discriminates melanoma from control tissues with extremely high efficacy." (PMID 33302400, 2020). "We therefore conclude that combined analysis of the expression of the MIP-1a, IL-1RA, IL-7, and MIP-1b genes represents the best combination within the 27 investigated, able to very effectively discriminate the control from the melanoma samples." (PMID 33302400, 2020). "Expression was confirmed to be significantly different in melanoma compared to the healthy controls, for IL-1Ra (recognized as ILRn by GEPIA2), IL-7, MIP-1a (recognized as CCL3 by GEPIA2), and MIP-1b (recognized as CCL4 by GEPIA2)." (PMID 33302400, 2020). "In contrast, when comparing samples from dogs with oral malignant melanoma to those without the disease, concentrations of IL-7 and MCP-1 were significantly higher in the absence of disease samples than in the OMM samples." (PMID 40711287, 2025). "Nonetheless, melanoma patients display reduced CD8+ T-cell cytotoxicity, suggesting that insufficient IL-7 may contribute to dysfunctional CD8+ T-cell responses and limit effective antitumor immunity." (PMID 40636453, 2025).
melanoma (continued). "Subsequently, they developed an LX/IL-7-based autologous tumor vaccine by loading irradiated B16-F10 murine melanoma or EL-4 murine lymphoma cells with LX/IL-7 (i.e., B16-LX/IL-7 or EL4-LX/IL7) and tested its antitumor efficacy, prophylactically and therapeutically." (PMID 40957993, 2025). "It has been demonstrated that using IL-7 to generate TCR-modified T cells in the absence of CD3 activation is a feasible strategy for enhancing over-the-counter T cell therapy for melanoma and other types of cancer." (PMID 38675377, 2024). "Systemic administration of IL-7–CBD and CBD–IL-12 in conjunction with suboptimal αPD-1 dose showed unprecedented tumor control without any overt toxicity in the autochthonous BrafV600E/Pten−/−/βCATSTA melanoma model." (PMID 38019919, 2023). "Thus, the aim of this study was to investigate the effect of IL-7 regulation on CD127 expression and CD8+ T cell responses in melanoma." (PMID 35850640, 2022). "IL-7 signaling through CD127 and PI3K pathway might be one of the potential therapeutic approaches to promote immune response for treatment of melanoma." (PMID 35850640, 2022). "TIL1383I TCR-modified T cells (gene-edited T cells expressing TCR reactive to melanoma antigen, tyrosinase) were co-cultured with IL-7 in the absence of CD34 activation." (PMID 36142322, 2022). "Thus, we further investigated the modulatory activity of exogenous IL-7 to CD127 expression and cytotoxicity of circulating and tissue-infiltrating CD8+ T cells in melanoma patients." (PMID 35850640, 2022). "Our study demonstrates that IL-7 and CCR2b co-expression in GD2-CAR-T cells exhibit stronger anti-tumor activity than classical second-generation CAR-T cells, shedding light on the potential novel GD2-positive neuroblastoma and melanoma treatment approach." (PMID 34778046, 2021). "In these studies, we demonstrate efficient T cell transduction with the melanoma-reactive TIL1383I TCR through culturing with interleukin 7 (IL-7) in the absence of CD3 activation." (PMID 34172810, 2021). "Compared to the control group, melanoma patients had higher levels of VEGF-A, PDGF-BB, IL-1RA, PIGF-1, IFN-γ, TNF-α, MIP-1α, and SCF, but lower levels of BDNF, SDF-1α, MCP-1, Eotaxin, EGF, and IL-7." (PMID 33574842, 2021). "In this study, melanoma patients showed higher levels of VEGF-A, PDGF-BB, IL-1RA, PIGF-1, IFN-γ, TNF-α, MIP-1α, and SCF, but decreased levels of BDNF, SDF-1α, MCP-1, Eotaxin, EGF, and IL-7 than those in healthy patients." (PMID 33574842, 2021). "As T cell activation likely yields a suboptimal therapeutic product, we aimed to generate melanoma-reactive TCR-modified T cells following culture with IL-7 rather than CD3 stimulation." (PMID 34172810, 2021). "In conclusion, we demonstrate efficient generation of melanoma-reactive TIL1383I TCR-modified T cells in the absence of activation by utilizing IL-7 treatment and a lentiviral vector." (PMID 34172810, 2021). "This study aimed to explore whether interleukin (IL)-7 and CCR2b expression could improve GD2-CAR-T cell survival and infiltration in neuroblastoma and melanoma treatment." (PMID 34778046, 2021). "In addition, the IL-7–CBD and CBD–IL-12 combination therapy overcame resistance to PD-1 blockade in an orthotopic triple-negative breast cancer model and in a genetically engineered melanoma model." (PMID 38019919, 2023). "Notably, patient carriers of the rs16906115 risk allele demonstrate significantly greater induction of B-cell-specific IL7, a context-specific effect not observed in those without melanoma or in other immune subsets." (PMID 36526722, 2022). "Moreover, IL-7 is known to regulate CD127 expression in CD8+ T cells through multiple mechanisms in vitro, and we previously reported the decreased expression of peripheral IL-7 in melanoma patients." (PMID 35850640, 2022). "However, unexpectedly, IL7-Fc accelerated the growth of B16-F10 melanoma in mice that received activated pmel-1 CD8+ T cells without lymphodepletion." (PMID 34440787, 2021).
melanoma (continued). "As IL-2 complex was administered to our melanoma tumor-bearing mice to support the infused CAL-101 T cells, we suspected that this cytokine was important for the engraftment of these infused cells and could compensate for IL-7." (PMID 29033940, 2017). "In order to assess the potential of interleukin 7 (IL-7) as an immunotherapeutic agent in human melanoma, we have evaluated the in vitro activity of IL-7-induced lymphokine-activated killer (LAK) cells from patients with advanced melanoma against allogeneic and autologous melanoma cells." (PMID 8018541, 1994). "IL-7 stimulation to CD8+ T cells from melanoma patients not only enhanced direct cytolytic function of CD8+ T cells to target cells, but also promoted IFN-γ and TNF-α secretion, indicating that IL-7 increased cytolytic and non-cytolytic activity of CD8+ T cells in melanoma patients." (PMID 35850640, 2022).
viral infection (40 papers, 2011 to 2025). "IL-7 is associated with improved immune response against bacterial and viral infections, and also in fungal sepsis and Pneumocystis infection; however, a direct correlation of IL-7 and paracoccidioidomycosis has not been evaluated yet." (PMID 31340551, 2019). "Use of IL-7 protein and IL-7 encoding DNA constructs are reported to be useful against cancer and many viral infections." (PMID 27051202, 2016). "A study demonstrated the participation of TLR2 in the activation of memory T CD8+ cells, during an established chronic viral infection in a murine model, causing an increase in the proliferation and expansion of these cells, induced by IL-7 both in vitro and in vivo." (PMID 38203441, 2023). "Finally, Campisciano detected an increase of the relative vaginal abundance of Prevotella timonensis in women infected with HPV, which showed a decreased concentration of the IL-15, IL-7, and IL-9 that they associated with the virus infection." (PMID 33488574, 2020). "Other implicated factors included Resistin with its pro-inflammatory effect and IL-7 with its influence on leukocyte development, malignancy, and viral infection." (PMID 36745304, 2024). "In viral infections, IL-7 promotes the production of memory-type T cells, and in the presence of IL-15 and the blocking of IL-2, IL-7 can accelerate the proliferation of T cells expressing the CD44 memory phenotype." (PMID 36936961, 2023). "In the case of viral infections, elevated levels of various inflammatory cytokines, including IL-1β, IL-6, IL-7, IL-17, IFN-γ, IL-8, TNFα, and GM-CSF are observed, alongside IL-4 and IL-5." (PMID 37692890, 2023). "Altogether, these in vitro and in vivo experiments suggest that lung epithelial cells are responsive to viral infection, and that during influenza infection, they become the primary source of IL-7." (PMID 34997007, 2022). "We further demonstrate that IL-7 is induced in the lung tissue by viral infection and we characterize multiple cellular sources that contribute to IL-7 production." (PMID 34997007, 2022). "Subsequent studies showed a role for IL-7 in memory cell development and maintenance, in effector response to viral infections and in enhancing T cell functions in chronic conditions." (PMID 34997007, 2022). "We have demonstrated for the first time that IL-7 is inducible in lung epithelial cells in response to viral infection in vivo." (PMID 34997007, 2022). "There were 14 trials (participants = 2329) that used cytokines such as IL-2 and IL-7 for lymphocyte activation or type I IFNs to induce innate immunity against virus infections." (PMID 34959492, 2021). "FRC and lymphatic endothelial cells up-regulate interleukin-7 (IL-7) expression responding to viral infection contributing to lymphocyte survival, remodeling, and reconstruction of the distinct lymph node microenvironment." (PMID 32187985, 2020). "The cytokine IL-7 is crucial for the survival of naïve and memory T cells, which are important effectors against several pathogens including viral infections." (PMID 31211814, 2019). "We now provide evidence supporting the use of IL-7 to reveal and expand in vivo-primed pathogen-specific lymphocytes of clinical relevance, either as biomarkers of viral infection and disease activity or as therapeutic tools." (PMID 29506153, 2018). "Earlier and stronger viral infection in the ileum compared to LNs or to other parts of the gut suggests that the presence of infected cells directly triggers local IL-7 production." (PMID 28579989, 2017). "IL-7 seems to be a promising molecule to be studied and tested further for increasing the effectiveness of vaccines, especially against viral infections." (PMID 27051202, 2016). "Cytokines and chemokines that showed limited response in mice with any viral infection included Eotaxin, GM-CSF, IL-1α, M-CSF, IL-2, IL-3, IL-4, IL-5, IL-7, IL-9, IL-12p40, IL-13, IL-15, IL-17, MIP2, LIX, MIP1β, RANTES, IL-12p70, and VEGF (data not shown)." (PMID 23441208, 2013).